IL6 (interleukin 6)
Diseases named in the same sentence as IL6 in open-access papers (continued):
Sharing a sentence is not in itself a finding about the gene and the disease.
endothelial dysfunction (continued). "This inflammatory response is further enhanced by increased IL-17A, TNF-α, IL-6, and other mediators involved in developing endothelial dysfunction." (PMID 40137170, 2025). "First, they promote endothelial dysfunction by upregulating pro-inflammatory cytokines (e.g., IL-6, TNF-, and downregulating anti-inflammatory mediators, thereby triggering vascular inflammation and compromising the integrity of the endothelial barrier." (PMID 41503037, 2025). "Elevated levels of IL-6 correlate with increased myocardial injury and worse clinical outcomes, while TNF-α and IL-1β have been implicated in endothelial dysfunction, smooth muscle proliferation, and cardiac fibrosis." (PMID 40724554, 2025). "Scientific evidence also suggests that inflammation (interleukin-6 and C-reactive protein), oxidative stress, and endothelial dysfunction play important roles in the pathogenesis of frailty." (PMID 39733527, 2024). "Chronic IL-6 signaling contributes to the maintenance of a pro-inflammatory environment, which exacerbates endothelial dysfunction and promotes the development of unstable atherosclerotic plaques." (PMID 39057626, 2024). "Elevated levels of advanced glycation end-products and pro-inflammatory cytokines like tumor necrosis factor-α and interleukin-6 in GDM further contribute to endothelial dysfunction and the development of PIH." (PMID 39356701, 2024). "In this context, the IL-6-mediated release of cytokines is thought to lead to endothelial dysfunction, including disruption of the blood-brain barrier (BBB)." (PMID 38910651, 2024). "The analysis of HDL’s role in mitigating endothelial dysfunction, as indicated by IL-6 production, showed lower effectiveness in individuals with low plasma HDLc concentrations compared to those with medium or high levels." (PMID 39456762, 2024). "Decreased lung function or resultant pulmonary hypertension correlates with endothelial dysfunction and increased levels of inflammatory mediators, such as C-reactive protein, interleukin-6, interleukin-8, and tumor necrosis factor-alpha." (PMID 38911586, 2024). "Concurrently, a decrease in inflammation markers, notably C-reactive protein (CRP) and interleukin-6 (IL-6), implies the attenuation of chronic inflammation, potentially reducing endothelial dysfunction, thrombotic events, and organ fibrosis." (PMID 38327940, 2024). "Markers of inflammation (CRP, LDH, IL6), endothelial dysfunction (ICAM1, VCAM1, E-selectin), coagulation (fibrinogen) and fibrinolysis (D dimers) are used in assessing disease severity, prognosis and treatment options." (PMID 38474287, 2024). "These markers reflect a pro-inflammatory phenotype (IL-6 and IL-8), endothelial dysfunction (Angpt-2), alveolar epithelial injury (SP-D), and soluble u-PAR is known to drive renal injury." (PMID 39507250, 2024). "Elevated androgen levels are associated with increased expression of inflammatory cytokines like TNF-α and IL-6, further exacerbating endothelial dysfunction and inflammation in PE." (PMID 39062815, 2024). "This study indicates that biochanin A can target AKT1 and TNF-α to alleviate endothelial dysfunction induced by IL-6 in Perthes disease, which provides a theoretical basis for the treatment of Perthes disease by using biochanin A." (PMID 38195507, 2024). "By stimulating the synthesis of acute phase reactants especially CRP, coagulation cascade, endothelial dysfunction, perpetuation of inflammatory responses and effects on lipid metabolism, IL‐6 can lead to the development and acceleration of CVD occurrence." (PMID 39160453, 2024). "Based on this, we further performed immunofluorescence and found that the expression of ICAM-1 increased and ZO-1 decreased after IL-6 intervention, indicating endothelial dysfunction at this time." (PMID 38195507, 2024).
endothelial dysfunction (continued). "Activation of NF-κB and NLRP3 inflammasome is associated with production of tumor necrosis factor-alpha (TNF-α), IL-1β, and IL-6 inflammatory cytokines leading to vascular damage, endothelial dysfunction resulting in hypertension and cardiovascular disease." (PMID 39081863, 2024). "It releases toxins, causing endothelial damage and oxidative damage in the body, and releases inflammatory cytokines, such as TNF-α, IL-6, and IFN-gamma, causing endothelial dysfunction." (PMID 38887349, 2024). "We demonstrated in vitro that the expression of ICAM-1 was increased and the expression of ZO-1 was decreased after IL-6 induced endothelial dysfunction." (PMID 38195507, 2024). "Mice with conditional overexpression of IL-6 in myeloid cells show systemic and vascular inflammation as well as endothelial dysfunction." (PMID 39015379, 2024). "Herein, we report the first evidence on the protective role of miR-148a-3p in endothelial dysfunction by ameliorating the cytotoxic effects of the inflammatory pathways following exposure to IL-6." (PMID 38791128, 2024). "Significant elevation of inflammatory and endothelial dysfunction markers include IL-6, IL-8, ICAM and VCAM can diagnose PAD patients even at Fontaine stage-I." (PMID 38961103, 2024). "We previously reported that nmMLCK participates in intermittent hypoxia‐induced endothelial dysfunction, resulting from IL‐6 secretion and endothelial permeability, in addition to its interaction with the NF‐κB pathway in LPS‐induced vascular inflammation." (PMID 36708245, 2023). "Vitamin D also reduces the risk of endothelial dysfunction by inhibiting other proinflammatory factors such as TNF-alpha and IL-6, which reduce the availability of NO and the activity of eNOS." (PMID 38068901, 2023). "The subsequent increased cytokine production (TNF-a and IL-6 in particular) further promotes endothelial dysfunction: IL-6 contributes to vascular permeability and TNF-a worsens glycocalyx disruption in both diseases." (PMID 36675530, 2023). "It has been shown that IL-6 induces oxidative stress, endothelial dysfunction, and coagulation cascade activation." (PMID 37699657, 2023). "Flow-mediated dilation (FMD) and reactive hyperemia index (RHI) were used to assess endothelial dysfunction, and we assayed high-sensitivity C-reactive protein, interleukin-6, fibrinogen, p-selectin, and myeloperoxidase as serum measures of inflammation." (PMID 37305426, 2023). "IL-6 induces endothelial dysfunction with expression of tissue factor and adhesion molecules via upregulation of angiotensin converting enzyme-2 receptor." (PMID 36869206, 2023). "Along with the endothelial dysfunction, elevated levels of IL-1β, IL-6 and TNF-α inflammatory cytokines contribute to atherosclerotic plaque formation and cardiac irritability." (PMID 36992409, 2023). "In particular, the endothelial dysfunction disrupts the regulatory balance by decreasing nitric oxide and promoting an increase of interleukin-6 (IL-6), tumor necrosis factor (TNF-α), and blood levels of CRP." (PMID 37568542, 2023). "Under diabetic conditions, endothelial function is impaired due to the elevation of TNF-α or IL-6, suggesting that these cytokines can also promote endothelial dysfunction in coronary arteries." (PMID 37005639, 2023). "The upregulation of inflammatory factors such as IL-6 and IL-8 are related to endothelial dysfunction, platelet activation, and active thrombosis." (PMID 36211709, 2022). "Polymorphisms of the IL-6 gene regulate the circulating plasma level of interleukin – 6, a pleiotropic cytokine, which plays critical roles in the acute inflammatory response and could trigger endothelial dysfunction and activation of the coagulation – fibrinolysis system." (PMID 35769472, 2022). "Previous studies have shown that TNF-α and IL-6 have atherogenic properties concomitantly with increased hCys and lead to endothelial dysfunction by vascular calcification." (PMID 35684085, 2022).
endothelial dysfunction (continued). "Endothelial dysfunction, an initial factor in early atherosclerotic lesion formation, is induced by NF-κB and downstream production of inflammatory cytokines, such as IL-6 and TNF-α." (PMID 36204587, 2022). "IL-6 can directly act on endothelial cells to increase superoxide production, thus leading to endothelial dysfunction." (PMID 35177953, 2022). "In turn, IL-6 seems to be involved in the pathogenesis of hypertension through its effects on vascular inflammation and stiffness, and endothelial dysfunction." (PMID 36247461, 2022). "IL-6 has been shown to play an essential role in atherogenesis by inducing endothelial dysfunction, enhanced expression of adhesion molecules, the proliferation of smooth muscle cells, leukocyte recruitment, and matrix degeneration." (PMID 35887619, 2022). "Amongst biomarkers of inflammation and endothelial dysfunction, IL-6 and P-selectin showed a statistically significant overall decrease in the serial measurement analysis from prior to CV to the 7–10 days after CV." (PMID 34689250, 2022). "Collectively, it can be concluded that the altered trophoblast invasion and spiral artery remodeling, as well as the endothelial dysfunction in PE, are interrelated with the immune maladaptation and disturbed homeostasis of IL-6 and IL-8." (PMID 36498901, 2022). "Mechanisms involved in this endothelial dysfunction are a consequence of excessive cytokine production and the host’s exacerbated pro-inflammatory response, particularly by the actions of IL-6 and TNFα, which are increased in critically ill patients." (PMID 36556051, 2022). "Some cytokines like tumor necrosis factor alpha (TNF-α) and interleukin-6 (IL-6) are also suggested to take part in the development of endothelial dysfunction and arteriosclerosis in GHD." (PMID 35106704, 2022). "Elevated levels of uric acid can lead to multiple organ dysfunctions through mechanisms of endothelial dysfunction, vascular smooth muscle cell proliferation, increased IL-6 synthesis, and as well as impairment of nitric oxide production." (PMID 35206484, 2022). "Its propagation is facilitated by inflammation and endothelial dysfunction, which release Il-6 as a response to the virus, resulting in an amplified host immune response and cytokine storm." (PMID 35887714, 2022). "Consistent with the previous notion, IL-6 is recognized as a circulating marker of endothelial dysfunction and increased levels have been observed in the sera of women suffering from PE." (PMID 36498901, 2022). "This prothrombotic state is possibly related to the increase in inflammatory cytokine levels (high sensitivity C-reactive protein (CRP), IL-6 and TNF-α), which are proatherogenic, decrease endothelial progenitor cell survival and cause endothelial dysfunction." (PMID 35207718, 2022). "IL-6 signaling mediates various effects on blood vessel walls, including endothelial activation, vascular permeability, immune cell recruitment, endothelial dysfunction, and vascular hypertrophy and fibrosis." (PMID 35887619, 2022). "The cytokines tumor necrosis factor alpha, interleukin-1 beta, and interleukin-6 have particular effects on endothelial cells—leading to endothelial dysfunction, endothelial cell death, changes in tight junctions, and vascular hyperpermeability." (PMID 35682871, 2022). "The production of IL-6 in aneurysm tissue is directly regulated by Ang II signaling; and IL-6 ablation protects from endothelial dysfunction induced by Ang II." (PMID 36275758, 2022). "IL6 levels in particular were highest in type H2 at time of presentation, and markers of endothelial dysfunction and coagulation were significantly higher in this type as well." (PMID 35665340, 2022). "Sleep fragmentation and recurrent arousals from sleep also induce endothelial dysfunction and recruitment of inflammatory cytokines, such as interleukin-6." (PMID 35886249, 2022).
endothelial dysfunction (continued). "Circulating levels of inflammatory cytokines such as tumor necrosis factor-a (TNF-a) and interleukin-6 (IL-6) are elevated in PE and interfere with the maternal endothelium to produce systemic endothelial dysfunction." (PMID 35329905, 2022). "In said context, PCSK9 deficiency reduces endothelial dysfunction by reducing the expression of lower endothelial expression of the genes encoding, e.g., ICAM-1, CCL2, IL-6 and IL-1β." (PMID 36361853, 2022). "Systemic lupus erythematosus (SLE)-like mouse models display endothelial dysfunction and cardiac hypertrophy, mediated through IL-6 and IL-1α." (PMID 33868242, 2021). "Particularly, IL-6, a well-known pro-inflammatory cytokine, participates in the pathological process of hypertension by promoting endothelial dysfunction and inflammatory cell recruitment." (PMID 33906674, 2021). "IL-6 dislocates the tight junctions in endothelial cells which leads to increased vascular permeability and endothelial dysfunction." (PMID 34681861, 2021). "IL-6 leads to hypercoagulability by promoting platelet activation, endothelial dysfunction, promoting coagulation factor disorders." (PMID 34945800, 2021). "TNFα induced endothelial dysfunction also significantly increased mRNA levels of IL-6, NLRP3 and PTGS2." (PMID 34362171, 2021). "Future studies are required to further explore and validate the value of IL-6 levels as a biomarker for endothelial dysfunction and cardiovascular disease." (PMID 33917744, 2021). "TNF-α, such as resistin and other pro-inflammatory cytokines such (e.g., interleukin-6, IL-6), acts by enhancing IR occurrence and it is closely related to the degree of endothelial dysfunction." (PMID 33578702, 2021). "Circulating cytokines, such as TNF-α and IL-6, are related to the degree of endothelial dysfunction in HF, which correlates with progressive deterioration in HF functional class." (PMID 33804661, 2021). "Other pro-inflammatory molecules are related to endothelial dysfunction, like IL-6, TNF-α, monocyte chemoattractant protein 1 (MCP-1), and the pro-oxidant enzyme NADPH oxidase, all of which predispose the vasculature to CVD." (PMID 33467601, 2021). "The proinflammatory cytokines, such as tumor necrosis factor (TNF)‐α and interleukin (IL)‐6, lead to endothelial dysfunction and activation, primarily in patients with RA." (PMID 34075600, 2021). "In the second stage, the ischemic placenta will experience oxidative stress and release inflammatory factors, such as IL-6, leading to systemic endothelial dysfunction." (PMID 33977108, 2021). "IL6 is a well-known multifunctional cytokine with reported roles in cardiovascular disease and endothelial dysfunction." (PMID 34479577, 2021). "The upregulation of vascular cell adhesion protein 1, intercellular adhesion molecule 1, monocyte chemoattractant protein 1, and IL-6 leads to endothelial dysfunction, monocyte recruitment, and inflammatory response." (PMID 34596673, 2021). "Endothelial dysfunction leads to cytokine release, including Il-1, Il-6 and TNF-alpha, culminating in increased blood brain barrier permeability." (PMID 34457265, 2021). "Inflammatory cytokines, such as interleukin-6 (IL-6) and 1 (IL-1), are considered as important contributors to endothelial dysfunction in T2D10." (PMID 33723367, 2021). "Patients with persistent HRF displayed higher biomarkers of inflammation (interleukin-6, interleukin-8) and endothelial dysfunction (angiopoietin-2) than resolving HRF after adjustment." (PMID 34526076, 2021). "Whereas most proteins induced significant changes in endothelial permeability, nsp2, nsp5_c145a (catalytic dead mutant of nsp5), and nsp7 also reduced CD31, and increased von Willebrand factor expression and IL-6, suggesting endothelial dysfunction." (PMID 34694226, 2021). "Elimination of IL-6 alone results in a much milder vascular manifestation with reduction in infiltrating leukocytes and recovery of endothelial dysfunction." (PMID 33669022, 2021).
endothelial dysfunction (continued). "Other pathogenic effects of IL-17A on endothelial dysfunction include the induction of the gene expression of chemokines and pro-inflammatory mediators, including IL-8, CCL20, IL-6 and IL-15." (PMID 33322218, 2020). "It has been suggested that IL-6 induces overexpression of angiotensin 2 type 1 receptors in vascular smooth muscle, resulting in oxidative stress and endothelial dysfunction; possibly linking these findings." (PMID 33122738, 2020). "Cytokine IL-6 is involved in the development of endothelial dysfunction by regulating the expression of the VCAM1 and ICAM1 genes, encoding intercellular adhesion molecules." (PMID 33659786, 2020). "In turn, oxidative stress triggers intravascular inflammation and endothelial dysfunction via the release of factors such as tumor necrosis factor-α (TNFα), interleukin-6 (IL6), IL10, C-reactive protein, and other factors, such as Hemoglobin F." (PMID 32679789, 2020). "A study on stable diabetic CKD patients revealed the ability of Salacia chinensis to forestall endothelial dysfunction, demonstrated by a decrease in the levels of homocysteine and IL-6." (PMID 32695828, 2020). "On other hand, miR-126 or miR-223 that are linked to arterial thrombosis target proteins that cause endothelial dysfunction, alternation of lipid metabolism or trigger inflammation and target ICAM-1, VCAM-1, IL-6 or IL-8." (PMID 32443696, 2020). "In our study, we found patients who had Child-Pugh B cirrhosis (CTP 7–9) showed higher plasma values of biomarkers linked to the inflammatory response (IP-10, IL-6, and OPG) endothelial dysfunction (sVCAM-1 and sICAM-1) and coagulopathy (D-dimer)." (PMID 32587340, 2020). "Endothelial dysfunction is reflected by biomarkers such as endothelin 1, homocysteine, and IL-6 (a proinflammatory cytokine)." (PMID 32695828, 2020). "Higher values of plasma biomarkers linked to an inflammatory response (IP-10, IL-8, IL-6, and OPG), endothelial dysfunction (sVCAM-1 and sICAM-1), and coagulopathy (D-dimer) were related to higher CTP values." (PMID 32587340, 2020). "In particular, IL-6 induces endothelial dysfunction, stimulates the formation of foam cells, reduces the production of HDL-cholesterol and has been associated with cerebrovascular events and peripheral atherosclerotic disease." (PMID 31110500, 2019). "Endothelial pathology is accompanied by excessive production of factors, called endothelial dysfunction markers, related to the inflammatory process, such as tumor necrosis factor—TNFα—or interleukin 6 (IL-6)." (PMID 30610442, 2019). "IL-6 is involved in systemic features of COPD, such as muscle weakness and endothelial dysfunction, while TNF-α is usually associated with airway inflammation through activation of the nuclear factor kappa B pathway." (PMID 31191356, 2019). "In turn, IL-17 induces IL-1β, IL-6, and TNF-α secretion, also associated with endothelial dysfunction and hypertension." (PMID 31186952, 2019). "Baicalein displayed anti-inflammatory effects by attenuating endothelial dysfunction and the inflammatory mediators, such as IL-33, IL-6, IL-1β, MMP-9, and IL-13, in radiation enteropathy." (PMID 31474856, 2019). "Increases of inflammatory cytokines TNFα and interleukin-6 were reported in regard to endothelial damage and are considered features of both endothelial dysfunction and early stages of plaque formation." (PMID 29615651, 2018). "A recent review highlighted the cellular and oxidative mechanisms of IL-6 signaling in the vasculature, including endothelial activation, vascular permeability, immune cell recruitment, endothelial dysfunction, as well as vascular hypertrophy and fibrosis." (PMID 29954107, 2018). "It is noteworthy that IL-6 is capable of inducing vascular smooth muscle proliferation that can lead to endothelial dysfunction and arterial stiffness." (PMID 29433433, 2018).